EZH2 (enhancer of zeste 2 polycomb repressive complex 2 subunit)
Diseases named in the same sentence as EZH2 in open-access papers (continued):
Sharing a sentence is not in itself a finding about the gene and the disease.
cancer (continued). "Pooled HRs > 1 indicated that high EZH2 expression would be correlated with poor OS in various cancers." (PMID 26683709, 2016). "Enhancer of zeste homolog 2 (EZH2), a dynamic chromatin regulator in cancer, represents a potential therapeutic target showing early signs of promise in clinical trials." (PMID 27835578, 2016). "EPZ-6438 (tazemetostat) is also an effective and orally bioavailable EZH2 inhibitor with anti-cancer activity." (PMID 27651838, 2016). "Accumulating evidence from in vitro and in vivo models together with studies in human cancers strongly suggest that EZH2 is involved in the development and progression of several human malignancies." (PMID 27793053, 2016). "Combined exposure to 5-aza-2′-deoxycytidine and GSK126 (EZH2 inhibitor) showed an additive inhibitory effect on growth of cancer cells in vitro and re-expression of tumor suppressor genes." (PMID 27651838, 2016). "The evidence indicates that EZH2 plays a role in the initiation, development, progression, and metastasis of cancer and drug resistance." (PMID 27502594, 2016). "The panel of human CRC organoids tested in our study shows a large variability in response to treatment with the EZH2 inhibitor GSK126, providing a rationale for using high-specificity EZH2 inhibitors as anti-cancer therapy for a subset of CRC patients." (PMID 27634879, 2016). "Particularly, as part of PRC2, EZH2 can affect the expression of numerous target genes that are critical for the survival, proliferation and aggressiveness of cancer cells, via epigenetic mechanisms." (PMID 27793053, 2016). "Regulation by EZH2 in other cancer types remains largely unstudied, especially for the lncRNA targets." (PMID 27835578, 2016). "It is well established that the PRC2 methyltransferase EZH2 functions as an oncogene in several cancers." (PMID 26755663, 2016). "We further mechanistically investigated the functional role of EZH2 in the regulation of cell proliferation, apoptosis, clonogenicity, cancer stem cell maintenance, cell migration, and invasive malignant behaviors in vitro." (PMID 27223261, 2016). "EZH2 is a well-known oncogene that is frequently upregulated in human cancers and is predictive of a poor prognosis." (PMID 27259264, 2016). "EZH2 is oncogenic in a wide variety of cancer types, functioning predominately as a transcriptional repressor that silences tumor suppressor gene targets." (PMID 26848980, 2016). "EZH2 has been studied extensively as a promoter of cancer progression through the induction of cell cycle and inhibition of cancer cell differentiation." (PMID 27793053, 2016). "Overexpression of EZH2 is often found in a variety of cancers such as breast, prostate, lung and blood cancers, with its expression level correlated with that of H3K27me3, more virulent progression of the disease, and poor prognosis." (PMID 27316347, 2016). "EZH2 ChIP sequencing data in 19 cell lines and RNA sequencing data in ten cancer types were downloaded from GEO and TCGA, respectively." (PMID 27835578, 2016). "The interest in better understanding of the role of EZH2 in cancer has been enhanced by the development of novel agents that inhibit EZH2 enzymatic activity, which are currently under evaluation in early phase clinical trials showing promising results." (PMID 27793053, 2016). "Recent studies suggest that EZH2 has significant implications in carcinogenesis and is a novel target in cancer therapeutics." (PMID 27199994, 2016). "In this study, we highlighted the role of EZH2 in regulating mRNA and lncRNA expression by integrating ChIP sequencing analysis in 19 normal and cancer cell lines and co-expression analysis in ten cancer types from TCGA data." (PMID 27835578, 2016). "Epigenetic silencing of tumor suppressor genes, including EZH2, in cancer has evoked the use of potential therapeutic strategies based upon inhibitors of epigenetic enzymes." (PMID 27471434, 2016).
cancer (continued). "More studies are needed to investigate the possible prognostic and therapeutic potential of HBP1, p21, and EZH2 in cancers." (PMID 27129219, 2016). "EZH2 is essential for proliferation and amplified in many primary cancers, and is inhibited by AKT through phosphorylation at Ser21." (PMID 26349457, 2016). "Increasing evidence indicates that elevated expression of enhancer of zeste homolog 2 gene (EZH2) in many human malignant tumors acts a significant role in the oncogenic process." (PMID 27706111, 2016). "Our previous study has demonstrated that GSK343, an S-adenosyl-L-methionine (SAM)-competitive inhibitor of EZH2, induces autophagy and enhances drug sensitivity in cancer cells including HCC." (PMID 26973856, 2016). "So far, a limited number of cancer types have been demonstrated to respond well to treatment with EZH2 inhibitors." (PMID 27634879, 2016). "EZH2 is overexpressed in several solid tumor types, and high expression is correlated with aggressive disease in specific cancers." (PMID 26848979, 2016). "It has been demonstrated that the inactivation of these subunits renders the cancer cells functionally dependent on the EZH2 catalytic activity, and the treatment with EZH2 inhibitors gave very promising results against tumors harboring SWI/SNF mutations." (PMID 27222667, 2016). "Targeted compounds inhibiting EZH2 have been introduced in cancer therapeutics with promising results in pre-clinical studies as monotherapies or in combination with traditional chemotherapy and are currently under evaluation in phase 1 and 2 clinical trials." (PMID 27793053, 2016). "EZH2 expression and activity in cancer cells is altered at genetic, transcriptional, post-transcriptional and post-translational levels." (PMID 27793053, 2016). "EZH2 plays important roles in the progress of cell fate decision, cell cycle regulation, senescence, cell differentiation and cancer." (PMID 27266699, 2016). "Our findings point to the possibility of exploring the potential of EZH2 inhibitors, already in clinical trials for other cancers, for IM." (PMID 27842164, 2016). "In terms of cancer-specific survival, significantly lower mortality was observed in patients with high EZH2 expression (log-rank test: P = 0.010) than in those with low EZH2 expression." (PMID 26871294, 2016). "It is believed that EZH2 affects the pathogenesis of cancer by multiple different mechanisms as it is involved in a various cell intrinsic molecular pathways." (PMID 27793053, 2016). "Since this seminal discovery, interest in the crucial roles of EZH2 in PCa and other types of cancer is increasing exponentially." (PMID 26657505, 2016). "Knockdown of EZH2 results in reduced proliferation, increased apoptosis, and diminished tumorigenicity in cancer cells." (PMID 27223261, 2016). "By using a TGF-β-inducible EMT model in OC cells, we show that EZH2 is required for maintaining the epithelial characteristics of cancer cells and that erasure of the H3K27me3 marks catalyzed by EZH2 permits transition to a mesenchymal state." (PMID 27563817, 2016). "PRC subunits such as Bmi1 and Ezh2 are often over-expressed in various cancers and are required for formation and maintenance of CSCs." (PMID 26930714, 2016). "All of these results are indicative of the critical role of EZH2 in cancer cell proliferation, migration, and invasion." (PMID 27223261, 2016). "The complexity of EZH2 regulation by multiple molecular pathways, most likely contributes to the variable implications of EZH2 aberrations in various types of cancer." (PMID 27793053, 2016). "Because EZH2 is overexpressed in several cancers, it has been considered that can function as a tumor-associated antigen (TAA)." (PMID 27793053, 2016). "EZH2 inhibition using UNC1999 also reactivated the expression of genes in pathways relevant to cancer such as apoptosis, ID signaling and cellular differentiation." (PMID 26755663, 2016).
cancer (continued). "There is growing evidence that EZH2 can be regulated at transcriptional and post-translational levels in cancers." (PMID 27223261, 2016). "Previous studies have shown that EZH2 also plays a role in cancer stem cell via regulation of stem cell gene expression." (PMID 27223261, 2016). "We employed this strategy effectively in two different cancer cell contexts using two different EZH2 inhibitors." (PMID 27875550, 2016). "As a core component of PRC2, EZH2 is highly expressed in various cancer types, including lung, colon, stomach, breast and prostate cancers." (PMID 26871474, 2016). "To strengthen a potential clinical significance, we screened and analyzed the differential expression of HBP1, EZH2, and p21 in some human cancers through the TumorProfile database." (PMID 27129219, 2016). "As EZH2 has been actively pursued as a therapeutic target for various cancers, its inhibitors were also examined for their potential effect on longevity." (PMID 27889707, 2016). "In PCa, expression of α2-integrin and EZH2 is observed in a small fraction of cancer cells, which is supportive for their role as stem cell marker." (PMID 27447616, 2016). "While it is clear that CDK mediated EZH2 phosphorylation is critical for the maintenance of H3K27me3 marks through the cell cycle, the role of this interaction in the fate and function of cancer cells warrants further investigation." (PMID 27793053, 2016). "Given the extensive implication of EZH2 on cancer development and progression, the introduction of EZH2 inhibitors has been an area of intense pre-clinical and clinical investigation." (PMID 27793053, 2016). "Enhancer of zeste homologue 2 (EZH2), a potential epigenetic silencer of tumor suppressor genes, is frequently highly expressed in a wide variety of human cancers." (PMID 27421653, 2016). "DNA methylation and transcriptional silencing of cancer genes have been shown to persist, despite the depletion of EZH2, suggesting that simultaneously inhibiting EZH2 would be more effective in reversing 3Me H3K27 and DNA methylation." (PMID 27938379, 2016). "In malignant neoplasms, as shown in gastric cancer, overexpressed lnc RNA 00152 needs to bind to EZH2 in order to exert oncogenic potential through recruiting the PRC2 to promoters of tumor suppressor (TS) genes p15 and p21." (PMID 27239242, 2016). "More recently, the polycomb protein enhancer of zeste homolog 2 (EZH2) was demonstrated to regulate cancer cell fate in response to DNA damage." (PMID 26973857, 2016). "For example, GSK126, an EZH2 competitive inhibitor, is undergoing phase I clinical trials for treating hypermethylation-related cancers." (PMID 27706111, 2016). "Previous studies have showed that expression of EZH2 was correlated with proliferation, differentiation, progression and metastasis in several cancer types including lung." (PMID 27421653, 2016). "Recent findings have indicated EZH2 is involved in the development and progression of various human cancers." (PMID 27092879, 2016). "As an oncogene, EZH2 presented high expression level in cancer cells through activation of MEK-ERK pathway to increase the amount of H3K27me355." (PMID 27857213, 2016). "Because EZH2 plays a diverse role in cancers, insight into the regulation of its signaling would likely aid the development of EZH2-targeted therapeutics." (PMID 27502594, 2016). "DZNep efficiently inhibits EZH2 after 8 h of treatment and can induce strong apoptotic cell death reaction in cancer cells beyond 48 h." (PMID 26939020, 2016). "The gene of EZH2, plays an important role in tumorigenesis and cancer progression through epigenetic gene silencing and chromatin remodelling." (PMID 26859127, 2016). "During the last ten years, EZH2 has generated much interest as a potential therapeutic target in cancer." (PMID 26497210, 2016). "On the other hand, it has been proposed that EZH2 regulates senescence in different biological contexts such as cancer or in primary cells." (PMID 27248655, 2016).
cancer (continued). "High EZH2 level is found to be positively correlated with the aggressiveness, metastasis and poor prognosis of cancer." (PMID 27882937, 2016). "The H3K27 methyltransferase enhancer of zeste homolog 2 (EZH2) is essential for many biological processes, including the regulation of immune responses, and is overexpressed in several cancers." (PMID 27148271, 2016). "It will be of interest to investigate if other types of cancer depend on the same genetic factors in their response to EZH2 inhibition." (PMID 27634879, 2016). "In this article, the results indicated that EZH2 highly expressed in 18 kinds of human cancers and the incidence of high EZH2 expression was 0.54 (95% CI: 0.47-0.61)." (PMID 26683709, 2016). "Because EZH2 is a central regulator of proliferation, migration, invasion, and stem cell properties of cancer cells, it is an appealing potential target for inhibition." (PMID 27793210, 2016). "Meta-analysis of high EZH2 expression status and OS in a variety of cancers was performed; 8252 patients in 43 studies for high EZH2 expression were included." (PMID 26683709, 2016). "Given the evidence for EZH2 being a cancer driver, the development of EZH2-specific inhibitors has been an active area of investigation." (PMID 27835578, 2016). "Polycomb site methylation has now been accepted as a hallmark of cancers, and so the enrichment of polycomb proteins, SUZ12 and EZH2, should be an innate quality." (PMID 26464434, 2016). "Polycomb-independent regulatory functions of EZH2 have been also recognized in other cancer models, where the protein cooperates with other transcription factors (such as the androgen receptor or NF-κB) to exert oncogenic properties." (PMID 27563817, 2016). "Elevated levels of the Polycomb Group (PcG) protein EZH2 are found in a wide range of cancer types, and are often correlated with poor prognosis." (PMID 27634879, 2016). "In order to better understand the molecular events impacted by EZH2 inhibition in human cancer cells, it is important to monitor inhibitor induced alterations in H3K27me3 patterns across the genome." (PMID 27875550, 2016). "For example, histone H3K27 methyltransferase EZH2 is upregulated in various types of cancer such as cancer of the breast, colon and prostate." (PMID 27340776, 2016). "Since GSK3β is known to be inactivated by AKT or ERK, our work suggests a direct role of the GSK3β-EZH2 pathway in this scenario and offers a rationale for enhancing GSK3β activity and/or targeting EZH2 in anti-cancer therapy." (PMID 27494834, 2016). "Studies from pharmaceutical company including GlaxoSmithKline and Novartis showed that, EZH2 has already been evaluated as therapeutic cancer target in drug discovery proceeding." (PMID 27784285, 2016). "While EZH1 is predominant in differentiated tissue, EZH2 is highly expressed in proliferating cells, such as embryonic and adult neural progenitors, and in a wide variety of cancer cells." (PMID 27248655, 2016). "Because of the deregulation of EZH2 in human PCa and many other cancer types, it becomes an ideal target for drug development." (PMID 26657505, 2016). "The advent of high-specificity small molecule inhibitors against EZH2 has reinvigorated the assessment of EZH2 as a potential anti-cancer therapeutic target." (PMID 27634879, 2016). "Single, small clusters of carcinoma cells were obscured in the stroma, and lobular cancerization was strongly evidenced by nuclear expression of EZH2 in some cases." (PMID 27113214, 2016). "Specifically, the transcriptional expression of SEMA3A is negatively EZH2-dependent in both human cancer and mouse model in vivo." (PMID 26043758, 2015). "Overall, these data have demonstrated that inhibition of EZH2 by honokiol in UBC cells can suppress cancer cell growth and inhibit tumorigenicity." (PMID 26484567, 2015). "EZH2 has been found to be over-activated or over-expressed in many cancer types, such as lymphoma, colon, prostate, breast, and lung cancer." (PMID 25923513, 2015).
cancer (continued). "Despite the main function of EZH2 is gene silencing through the methylation of H3K27, several studies have shown that EZH2 acts as trascriptional activator in various types of cancer independently from H3K27me." (PMID 26268310, 2015). "This study aimed to explore the associations between enhancer of zeste homolog 2 (EZH2) and patient survival in various cancers." (PMID 25974088, 2015). "Overexpression of EZH2 in cancer was proposed to result from gene amplification, down-regulation of microRNA 101 (miRNA-101), and stimulation of its expression by the pRB–E2F and MEK–ERK pathways." (PMID 26637281, 2015). "This indicates a possible role of EZH2 in both, the pathogenesis and growth progression of PA in general, which is in line with several other mainly malignant tumor entities (reviewed in9)." (PMID 26593398, 2015). "Our results provide evidences that EZH2-EED interaction is a target for the treatment of PRC2-dependent cancer and wedelolactone is a candidate for modifications in the future." (PMID 25944687, 2015). "In light of this, we should consider preoperative treatment when applying EZH2 status to predict the OS of patients with cancer." (PMID 25974088, 2015). "Elevated expression of EZH2 has been observed in different human cancers, which we found to be upregulated in CRC in the current study as well." (PMID 25611389, 2015). "Evidences show that down-regulation of DAB2IP in cancer is mediated by polycomb EZH2 and histone deacetylase." (PMID 26336990, 2015). "Recently, several studies about EZH2 regulating cell invasion in various types of cancer showed that one of the major EZH2 PRC2-dependent function is promoting cell invasion." (PMID 25944687, 2015). "It has been reported that ablation of EZH2 in tumor cells using RNA interference technology suggested that the enzyme is a promising drug target for cancer treatment." (PMID 26258118, 2015). "Enhancer of zeste 2 polycomb repressive complex 2 subunit (EZH2), a polycomb group protein, has been identified as an oncogene in many types of cancers." (PMID 26362062, 2015). "Differential gene expression and correlation network analyses revealed that EZH2 is the most significantly over-expressed ERG in cancer and is co-regulated with a cell cycle network." (PMID 26110843, 2015). "Examples include, genes down-regulated by EZH2, a well known stem cell gene involved in the pathogenesis of several cancers and which plays a documented role in both breast and lung CSCs." (PMID 25793737, 2015). "Westerns revealed that SUZ12, EZH2 and/or H3K27me3 levels were typically elevated in cancer lines compared to non-cancer lines." (PMID 26030458, 2015). "Here we identify and characterize H1.2, one of the H1 subtypes, as a new effector protein that recognizes EZH2-mediated H3K27me3 to trigger chromatin compaction and gene silencing in cancer cells." (PMID 26581166, 2015). "DZNep has been shown to be effective in inducing apoptosis in a variety of cancer cells both in vitro and in vivo and has been used as a useful tool for studying EZH2-mediated gene silencing." (PMID 25928216, 2015). "Three UBC cell lines with various EZH2 expression levels show well response to honokiol treatment, suggesting that anti-cancer effects of honokiol is more general in UBC cells." (PMID 26484567, 2015). "Many cancers show aberrant silencing of gene expression and overexpression of histone methyltransferases, including EZH2 and EHMT1/2." (PMID 26300989, 2015). "HOTAIR targets PRC2 to hundreds of genes involved in the inhibition of cancer progression, and its depletion abrogates the capacity of EZH2 to induce cancer matrix invasion." (PMID 26029238, 2015). "Overall, our microarray results establish the functional interaction between H1.2 and EZH2 leading to transcriptional inactivation of particular sets of genes in cancer cells." (PMID 26581166, 2015).